CD68 (CD68 molecule)
Diseases named in the same sentence as CD68 in open-access papers (continued):
Sharing a sentence is not in itself a finding about the gene and the disease.
tumor (continued). "Tumor size was significantly inversely correlate with CD8 (p = 0.0257), CD68 (p = 0.0457), S100 (p = 0.0035), PNMT (p = 0.0009) and positively correlated with PASS (p = 0.0710) and GAPP score (p = 0.0006)." (PMID 33244312, 2020). "In this study, we found that there was significant positive correlation between NMU expression level and M2 macrophage percentage (CD206/CD68) in HCC peri- and intra-tumor tissue." (PMID 32013887, 2020). "Next, we generated differential gene expression plots between CD68 or CD163 high and low tumor samples." (PMID 32809114, 2020). "Because SR-A is a marker of differentiated macrophages, we compared the expression pattern of CD68, CD163, CD14 and SR-A in CHL tumor microenvironment." (PMID 31714922, 2019). "The CD68+, CD68+CD206++ and CD68+CD163+CD206+ macrophages were abundant in all ROI but given their dominant presence in the adjacent normal tissue (white circle), they could be associated with the normal-tissue macrophages more than tumor-associated macrophages." (PMID 31477692, 2019). "Since immunohistochemical stainings in serial PDAC tissue sections revealed a high abundance of CD68+ and CD163+ TAMs within tumor areas with marked PD-L1 expression, our data suggest that TAMs represent one of the PD-L1 expressing stromal populations." (PMID 30899426, 2019). "Our immunocytochemical data demonstrated that CD68 and CD163 positive infiltrating cells represent the cell types actively synthesizing C1q in the tumor micro-environment." (PMID 31649675, 2019). "In contrast, CD68+IRF8+ macrophages, were more abundant in the core compared with the margin, and were located within the tumor-nest than in the stroma." (PMID 31477692, 2019). "To understand the relationship among CD47, PD-L1, and TAM in PDAC, we stained the tumor specimen from 106 PDAC patients with anti-CD47, anti-PD-L1, anti-CD68, and anti-CD163 antibodies." (PMID 31771616, 2019). "It would be important to clarify if the quantifications of CD68 and CD163 were performed in exactly the same tumor regions." (PMID 31481956, 2019). "Our results showed increase CD68 staining in tumors compared to ANM, supporting the idea that these cells migrate towards the tumor site by chemotactic signals." (PMID 31481956, 2019). "Immunostaining of serial tumor sections confirmed that CLIC4 expression was lower in tumor than stroma and that immune cell infiltrates positive for CD3 (T cells) and CD68 (monocytes) were abundant in the stroma." (PMID 31921386, 2019). "Because of PTX3 overexpression, tumor samples were also characterized by a significant reduction of CD4+ and CD8+ lymphocyte, mast cell and CD68+ macrophage pro-inflammatory populations." (PMID 31533326, 2019). "Furthermore, a considerably higher proportion of freshly-isolated CD68+ macrophages from dispersed rat lung tumours of rats administered rat MOv18 IgE were found to express intracellular TNFα, an M1 macrophage marker, compared to MOv18 IgG2b and vehicle-treated tumours." (PMID 31544825, 2019). "This was confirmed in the current set of 43 tumours, by determining the numbers of lymphocytes (CD3+, CD4+, CD8+, FoxP3+; using immunofluorescence (IF)) and macrophages (CD68+, CD163+, CD68+CD163+; using IF)." (PMID 31337000, 2019). "The expression of B7-H3 in tumor/parenchymal cells was more strongly correlated with CD8-positive and CD68-positive cell infiltration and was markedly enhanced at the stages of neoplasia and GAC." (PMID 31998637, 2019). "However, at tumor stroma neither CD163 nor CD68 expression was associated with the EMT program." (PMID 30927925, 2019). "In our data, we found the CD68+IRF8+, CD68+CD206+, and CD68++CD163+ macrophages to be co-localized in the same tumor and were correlated with the increase of IL-1-, IL-6-, and IL-10-associated pathways, respectively." (PMID 31477692, 2019).
tumor (continued). "Higher densities of CD68+CD163+, CD68++CD163+, and CD68+CD206+ macrophages were found within the tumor regions when compared with normal tissues suggesting that these populations were polarized according to their location in the tumor microenvironment." (PMID 31477692, 2019). "Using immunohistochemistry, we examined tumor-infiltrating CD68+ pan-macrophages (CD68+ M) and CD163+ M2 macrophages (CD163+ M2) and tumor expression of CD47 and PD-L1 proteins in 106 cases of PDAC." (PMID 31771616, 2019). "Suppressive tumour polarised CD33+ cells down-regulated HLA-DR and upregulated CD68 consistent with a M1-like phenotype." (PMID 31462392, 2019). "Recently, CD68-positive cells have been reported to be a poor prognostic factor and TAMs recruitment in SHH expression tumor recruit TAMs significantly." (PMID 31744214, 2019). "The variables of CD47 expression, CD68+ M or CD163+ M2, tumor diameter, N stage, and grade were included in the multivariate analysis." (PMID 31771616, 2019). "Combined analysis of the expression of miR-21 in CD68+ cells of TI and the TME showed a slight reduction in patients’ survival when miR-21 is high in tumor macrophages." (PMID 31710308, 2019). "Surprisingly, the CD68+CD163+CD206+ macrophages, expressing both M2-like markers, were abundant in the tumor regions but were consistently located furthest from the tumor cells." (PMID 31477692, 2019). "For example, percentages of CD68-positive cells in the tumor-nest and TME compartments had a Pearson correlation coefficient (ρ) of 0.73, which fell to 0.42 when comparing CD68 and CD8 in the TME alone." (PMID 29874226, 2018). "We assayed hepatic levels of CD68 (a marker of macrophagic infiltration) and myeloperoxidase (MPO) (a marker of neutrophil infiltration) in HCC tumor specimens, matching paracancerous specimens, and normal liver specimens." (PMID 29445190, 2018). "Cell densities and percentages of 8 cell subpopulations [CD8+; CD68+; PD-1+; (PD-1+/CD8+); (CK+/Ki67+); (CK+/PDL1+); (CD68+/PD-L1+), and (CD8+/Ki67+)] were evaluated in tumor epithelium and stroma compartments." (PMID 30400822, 2018). "Pearson correlation revealed, that Gal3 expressing cells show a significant positive correlation with CD68 positive macrophages and MRC1 positive M2 macrophages in the IFZ of tumor-free cervical lymph nodes." (PMID 30115022, 2018). "Using a full panel of immune cell markers (CD3, CD8, PD1, Foxp3, CD68 and CD163), we asked how similar different tumor types were in terms of immune cell spatial layout." (PMID 30179157, 2018). "The invasive front, especially regions where budding cells were identified, showed a strong enrichment in CD68- and CD163-positive macrophages when compared to the tumor core (5,5-fold (p<0.001) and 3,5-fold (p= 0,0052 respectively)." (PMID 29731961, 2018). "Together, these data indicate that among mast cells, the stained with CD68 surface marker constitute the main cellular source of polyP, in CRC, and are localized in tumor stroma next to cancer cells and neutrophils." (PMID 29543850, 2018). "HE and IHC analysis of the CD68 and CD163 macrophage markers of pre-vaccine, post-chemotherapy FFPE tumor of Patient #3." (PMID 30326856, 2018). "Altogether, the data demonstrate higher densities and closer proximities of CD68+ and CD163+ pixels in tumor and T cell regions compared to CD11b+ and CD11c+ pixels." (PMID 30619287, 2018). "Baseline tumor samples (FFPE) were stained with multiplex immunofluorescence (mIF) for PD-L1, PD-1, CD3, CD8, CD68, and pancytokeratin in a single panel, scanned with the Vectra 3.0TM multispectral microscope, and analyzed using inFormTM 2.3.1 software." (PMID 30400835, 2018). "In summary, densities of CD68+ and CD163+ pixels are greater within and close to the edge of the tumor, consistent with attraction of macrophages by the tumor while CD11b+ and CD11c+ pixels reside at a greater distance from the tumor." (PMID 30619287, 2018).
tumor (continued). "When applying a 5% PD-L1 tumor-nest cut-off, 70% of samples segregated to the high PD-L1 group, with CD8, Granzyme B, and CD68 significantly higher in those samples (P < 0.05)." (PMID 29874226, 2018). "The number of each cell-type and location in tumour nest or stroma was determined for total T cell (CD3), CD8 T cells (CD8), T-reg (FoxP3) and macrophages (CD68) and related to survival by Kaplan-Meier analysis." (PMID 29416729, 2018). "While the greatest percentage (~70%) of CD68+ and CD163+ pixels was 0–20 microns away from tumor and T cell borders, CD11b+ and CD11c+ pixels were detected up to 240 microns away from tumor/T cell masks." (PMID 30619287, 2018). "We found that tumors were highly infiltrated by macrophages (F4/80+, CD68+, CD206+) that surround proliferating tumor cells (Ki67+), which also express phosphorylated/activated insulin/IGF-1 receptors." (PMID 29367764, 2018). "The tumor cells were diffusely positive for factor XIIIa and ALK, but were negative for AE1/AE3 keratin, alpha-smooth muscle actin, CD30, CD34, CD68, PU.1, melan A, MITF, and S-100 protein." (PMID 29747676, 2018). "Supporting this finding, immunohistochemistry against CD68 and CD3 revealed myeloid-derived (CD68+ve) and lymphoid-derived (CD3+ve) cells variably infiltrating the reactive glial and tumour epithelial compartments within human ACP." (PMID 29541918, 2018). "Accumulating evidence has suggested that not only a high frequency of CD163+CD68+ TAMs, but also a high amount of CD163 in serum or in tumor are correlated with a poor prognosis in patients with cancer." (PMID 29456539, 2018). "The number of CD68+ cells was similar in both high (++& +++) and low (−&+) PKN2 expression tumor tissues." (PMID 29368606, 2018). "Similar results were observed in tumor tissues from HCC patients and revealed a significant positive correlation between tumor B3GALNT2 levels and the number of CD68-positive macrophages in the HCC microenvironment (R = 0.325, p < 0.001)." (PMID 29618368, 2018). "In contrast to CD68+, CD39 was found only on tumor vasculature, whereas Arginase II and CD33 expression was virtually absent." (PMID 30054667, 2018). "High infiltration of CD68+ or CD163+ TAMs was consistently and significantly related to old age, large tumor size, advanced TNM stage, and adjuvant chemotherapy (all P < 0.050)." (PMID 29573574, 2018). "Significantly more CD68+ and CD163+ vs. CD11b+ and CD11c+ pixels were in direct contact with tumor cells and T cells." (PMID 30619287, 2018). "On the other hand, tumor-bearing TLR4−/− TB mice presented less adipocyte atrophy and a reduction in the number of TNF-α and CD-68 positive cells in scAT when compared to WT TB group." (PMID 30575787, 2018). "CD68+ or CD163+ TAMs showed a uniform density in the tumor stroma, TCA, TIF and were also present in necrotic tumor regions." (PMID 30038715, 2018). "Analyzing data from a single slide, the Pearson correlation coefficients of cell type densities outside and inside tumor regions were highest for CD4 + T-cells (r = 0.8), CD8 + T-cells (r = 0.68) or CD68+ macrophages (r = 0.79)." (PMID 28923066, 2017). "The tumours were immunostained for T-cell (CD3, CD8), natural killer (NK)-cell (CD56) and macrophage (CD68) markers and quantitative analysis of the immune cells was carried out using a computer-assisted image analysis in different tumour locations." (PMID 29269742, 2017). "We prepared serial slices of whole tumor cross-sections of the Myc-CaP and TRAMP-C2 tissues and stained them with either Prussian blue iron(III) to detect HLMs, or with CD68 marker." (PMID 28912459, 2017). "We have previously shown that MLL-tumors and TINT contain more CD68+ macrophages (pan macrophage marker) compared to AT1 and that these macrophages can stimulate tumor growth." (PMID 28472073, 2017). "The tumor stromal cells expressing α-SMA, CD68, CD163, and IL-6 were evaluated in B viral multistep hepatocarcinogenesis." (PMID 28114366, 2017).
tumor (continued). "To understand the extent of overlap between F4/80- and CD68-expressing macrophages in MMTV-PyMT tumors, we performed flow cytometry on dissociated tumor tissue." (PMID 29220404, 2017). "IF staining of CD68 and CD68+CD163+ showed that the majority of macrophages belong to the M2 phenotype, suggesting a potential tumor-favorable environment created by macrophages in CM." (PMID 28903377, 2017). "Tumor infiltrating lymphocytes as well as its FOXP3+, CD68+, IL-17+ phenotypes in both intratumoral and stromal sites and expression of FOXP3 in cancer cells were assessed." (PMID 28029650, 2017). "CD68+ and/or CD163+ myeloid cells (including macrophages and myeloid dendritic cells) were found in the stromal regions within the center of the tumor, demarcated by the cytokeratin+ tumor cells." (PMID 28344870, 2017). "We observed CD3+ T cells, CD20+ B cells and CD68+ monocytes/macrophages as well as Foxp3+ Treg cells and CD163+ TAMs to be present in peri- and intra-tumor areas." (PMID 29190964, 2017). "Intravenous injection of MSCs reduced the presence of CD3+ T lymphocytes, CD4+ T helper cells, CD68+ macrophages, TNF-α-producing, and IL-17-producing cells in the lungs of LLC1-treated mice 28 days after tumor induction." (PMID 28798777, 2017). "The cell populations inferred from this analysis were readily matched to the tumor cells and infiltrating lymphocytes, including macrophages and T cell classes, based on the specific expression of known markers such as CD3D and CD68." (PMID 29079795, 2017). "IL-6 (+) tumor stromal cells also showed positive correlations with α-SMA (+) CAFs, CD68 (+) and CD163 (+) tumor stromal TAMs." (PMID 28114366, 2017). "In the 38 CRCs included in our cohort, both CD68-positive cells and CD163-positive cells were almost exclusively located in the tissue surrounding the tumors, especially along invasive tumor front." (PMID 28403223, 2017). "To evaluate the in situ distribution of different Mφ subpopulations, we used immunostaining to detect CD68+ Mφs, CD204+ Mφs, and CD169+ Mφs in the non-tumor (NT) and intra-tumor (IT) areas of HCC and GC." (PMID 28202073, 2017). "Infiltration of CD68-positive macrophages and CD163-positive M2 macrophages was found in tumor tissue of AITL." (PMID 29100307, 2017). "In these GRP78-inhibited tumors, the CD68 positive macrophage population was significantly increased, suggesting that targeting UPR signaling has critical effects on the tumor microenvironment." (PMID 29113324, 2017). "The objective of this study was to evaluate the prognostic significance of elevated density of CD68+ and CD163+ TAMs in the tumor microenvironment on overall survival (OS) and PFS in patients with adult cHL." (PMID 27745550, 2016). "PD-L1 expressions in tumor cells (TCs) and TIICs, as well as infiltration of lymphocytes (CD4+, CD8+, FOXP3+, and PD- 1+) and macrophages (CD68+ and CD204+), were evaluated." (PMID 27322149, 2016). "In this study, we assessed the expression of two TAMs markers CD68 and CD163 in tumor or peritumoral tissue specimens." (PMID 26769084, 2016). "Some studies have found that TAMs promote tumor progression in CRC patients; CD68+ macrophages are used as a marker of progression, and CD163+ macrophages are associated with early local recurrence and reduced survival times." (PMID 27683110, 2016). "Immunohistochemically the tumor cells showed an expression of the histiocytic markers (CD4 and CD68) as well as of smooth muscle cell markers SMA and H-Caldesmon." (PMID 28018701, 2016). "We also observed the strongest CD68+ and CD163+ TAM infiltration in the tumor stroma and lamina propria." (PMID 27221038, 2016).
tumor (continued). "Immunohistochemical staining revealed that tumor samples taken at baseline before treatment had variable numbers of CD3+ cells, CD8+ cells, CD4+ cells, CD68+ cells, CD163+ cells, and CD11c + cells." (PMID 26981247, 2016). "A variety of markers (including CD68, CD163, CD204, HLA-DR, etc.)were used to identify different types of TAMs and the micro-distribution (in the tumor islet, stroma, or both) of TAMs in the tumor tissues." (PMID 27144518, 2016). "Tissue analysis for our patient showed the tumor cells stained positive for CD31, CD34, CD68, S-100, vWF, and Ki-67." (PMID 27651973, 2016). "Both patients’ specimens showed a similar composition of CD68-positive macrophages and CD8-positive T-cells as a percentage of total T-cells in the pre- and post-BMT tumor." (PMID 27685855, 2016). "We then further evaluated the expression of CD31, CD68, and CD206 in the same specimens and found that CD206+ M2Mφs was also increased in recurrences, while the recurrent tumours showed lower levels of CD31 vasculature." (PMID 27271009, 2016). "Immunohistochemically there was an expression of histiocytic markers (CD4, CD68) as well as smooth muscle cell markers (SMA, H-Caldesmon) in the tumor cells." (PMID 28018701, 2016). "Distribution features of CD1A, CD123, CD57, CD66b, CD68 and IL-13 were detected in 20 ESCC patients’ tumor tissues with IHC staining." (PMID 26771842, 2016). "M2 macrophages express the surface markers CD68 and CD206 and contribute to tumor progression by releasing a variety of cytokines, including chemokines, inflammatory factors, and growth factors." (PMID 27034164, 2016). "It has been reported that both CD68 and CD163 express on circulating monocytes and macrophages and used as TAMs markers in tumor progression." (PMID 26769084, 2016). "An inclination to the correlation with better tumor differentiation was seen for UCP1 and CD68 protein expression in patients with MHO and with worse (high grade) differentiation—for CD68 expression in the group with SO." (PMID 27853670, 2016). "So the correlation between density of CD68 as well as IL-13 in tumor stroma and patients’ survival time was further confirmed by a TMA containing 194 ESCC tumor samples from the same center (training set)." (PMID 26771842, 2016). "We used double staining with the primary antibody cocktail of CD31 plus CD39 and CD39 plus CD68 and found CD39+ cells (red) were more in tumor than in peritumoral tissue (×100)." (PMID 27749555, 2016). "Immunohistochemical studies displayed that CD163, CD11c, Mac387 and CD68 (both KP1 and PGM clones) were diffusely positive, which verified that the neoplasm cells were of histiocytic origin." (PMID 27535029, 2016). "Differences in the numbers of CD68+ and CD163+ macrophages in the tumor microenvironment of cHL have already been shown by others and by us." (PMID 25978381, 2015). "The tumor cells of BPDCN and PPDM share the common characteristic phenotype of pDCs: lin−, CD4+, CD68+, CLA+, CD123+, BDCA2+, Bcl11A+ and CD2AP+." (PMID 25779340, 2015). "Immunohistochemical analysis also exhibits specific staining patterns, as the tumor shows immunoreactivity with factor 8, CD31 and CD68, which indicates the presence of endothelial and histocytic cells." (PMID 25789041, 2015). "This analysis showed that small AT-1 tumors were more effective than small G tumors in recruiting CD68+ and CD163+ macrophages, and in stimulating vascular growth, to the tumor-bearing organ." (PMID 26536349, 2015). "For this purpose the macrophage markers CD11b and CD68 were used in combination with FOLR2 probes in both normal and tumor tissues." (PMID 25971554, 2015). "Homotypic CICs between tumor cells (CD45−/CD68−) (54%) were similar in number to heterotypic CICs (CD45+/CD68−, CD45−/CD68+, CD45+/CD68+)." (PMID 26109430, 2015). "At baseline patient R356 had more (CD3 x33, CD4 x10, CD8 x9, CD11c x21, CD68 x15, CD163 x12) immunological cells in the tumor than patient O340." (PMID 25714011, 2015).